ATP7A (ATPase copper transporting alpha)
Diseases named in the same sentence as ATP7A in open-access papers (continued):
Sharing a sentence is not in itself a finding about the gene and the disease.
anaemia (2 papers, 2013 to 2024). "Despite the anemia and probable intestinal hypoxia in MoBr/y mice, documented Hif2α targets in duodenal enterocytes (e.g. Dmt1, Fpn1, Atp7a) were not induced." (PMID 23776592, 2013).
coronary artery disease (2 papers, 2025). "ATP7A and PHKA1 are likely related to the cardiovascular system, EBP is associated with coronary heart disease and skeletal-related conditions, ZFX is known to be involved in animal size and ovarian failure, and SMC1A is implicated in premature ovarian failure." (PMID 39940742, 2025).
dysautonomia (2 papers, 2021 to 2024). An acute or chronic disorder, affecting the sympathetic or parasympathetic nervous system. "While there is no report of male infertility in ATP7A-related disease literature, retrograde ejaculation is a known symptom of dysautonomia associated with deficiency of dopamine-beta-hydroxylase (DBH), a copper dependent enzyme." (PMID 38141875, 2024). "Notably, all ATP7A-related phenotypes except SMAX3 show pale skin color and dysautonomia." (PMID 33917579, 2021).
esophageal carcinoma (2 papers, 2023). A primary or metastatic malignant neoplasm involving the esophagus. "Serum levels of Cu, CP, ATP7A/7B, and the Cu:Zn ratio in serum are result-related markers and are resistant to treatment across the entire spectrum of gastrointestinal tumours including gastric and oesophageal cancers." (PMID 36839370, 2023). "Moreover, some CRGs, including PIH1D2, SLC23A2, SLC25A5, ATP7A, PDHX and COX7B, were reported to be tightly linked with the grading and immune infiltration of esophageal carcinoma." (PMID 37380924, 2023).
gastric cancer (2 papers, 2021 to 2022). A primary or metastatic malignant neoplasm involving the stomach. "Effective blockade of the STAT3 activity by STAT3 inhibitor sensitized gastric cancer cells to cisplatin and reduced the cisplatin‐resistant‐related gene G3BP2, THOC1, ATP7A, and OTUD1 expression." (PMID 34375503, 2021). "Effective blockade of STAT3 activity by the STAT3 inhibitor stattic sensitized gastric cancer cells to cisplatin and reduced expression of the cisplatin resistance‐related genes G3BP2, THOC1, ATP7A, and OTUD1." (PMID 34375503, 2021).
Hermansky-Pudlak syndrome (2 papers, 2017 to 2025). Hermansky-Pudlak syndrome (HSP) is a multi-system disorder characterized by oculocutaneous albinism, bleeding diathesis and, in some cases, neutropenia, pulmonary fibrosis, or granulomatous colitis. "The trafficking of ATP7A to melanosomes depends on the biogenesis of lysosome-related organelles complex-1 (BLOC-1), and defects in this pathway lead to mislocalization of ATP7A, impaired tyrosinase activity, and hypopigmentation, as observed in certain forms of Hermansky-Pudlak syndrome." (PMID 40943549, 2025).
lung adenocarcinoma (2 papers, 2016 to 2018). A carcinoma that arises from the lung and is characterized by the presence of malignant glandular epithelial cells. "Overexpression of miR-495 increased the chemosensitivity of platinum-resistant lung adenocarcinoma cells by inhibiting copper-transporting P-type adenosine triphosphatase A (ATP7A), a gene of multi-drug resistance." (PMID 27075472, 2016).
major depression (2 papers, 2023 to 2024). "In addition, our previous investigation showed that the mRNA expression levels of ATPase copper-transporting alpha (ATP7A) decreased in patients with major depression." (PMID 37434135, 2023).
mental disorder (2 papers, 2017 to 2024). A disease that has its basis in the disruption of mental process. "Moreover, 181 gene products contained in the ATP7A interactome were associated with mental disorders (Medical Subject Heading F03, p<0.0001)." (PMID 28355134, 2017).
Myocardial fibrosis (2 papers, 2023 to 2025). "According to the findings, SIRT7, by controlling YAP/ATP7A signaling, lowers cuproptosis, myocardial fibrosis, and cardiac dysfunction in hypertensive conditions." (PMID 41567643, 2025).
prostate carcinoma (2 papers, 2020 to 2025). A carcinoma that arises from epithelial cells of the prostate gland. "In prostate cancer, elevated levels of CTR1, ATP7A, and ATP7B have been observed." (PMID 41516324, 2025).
pulmonary hypertension (2 papers, 2014 to 2021). Increased pressure within the pulmonary circulation due to lung or heart disorder. "Interestingly, there are reports of patients with mutations in ATP7A causing structural abnormalities of the pulmonary circulation and pulmonary hypertension." (PMID 34068984, 2021). "ATP7A is upregulated in the lung tissues and pulmonary arteries of mice with hypoxia-induced pulmonary hypertension." (PMID 34068984, 2021). "In this study, we show that the Cu-uptake transporter 1, CTR1, and the Cu-efflux pump, ATP7A, were both upregulated in the lung tissues and pulmonary arteries of mice with hypoxia-induced pulmonary hypertension." (PMID 24614111, 2014). "In summary, the data from this study indicate that increased Cu transportation due to upregulated CTR1 and ATP7A in pulmonary arteries and PASMC contributes to the development of hypoxia-induced pulmonary hypertension." (PMID 24614111, 2014).
Breast invasive carcinoma (1 paper, 2020). "Survival analyses of ATP7A and ATP7B were used to evaluate their effects on the development of Breast invasive carcinoma (BRCA)." (PMID 32508020, 2020).
cholangiocarcinoma (1 paper, 2025). A carcinoma that arises from the intrahepatic biliary tree (intrahepatic cholangiocarcinoma) or from the junction, or adjacent to the junction, of the right and left hepatic ducts (hilar cholangiocarcinoma). "In cholangiocarcinoma (CCA), a 4-gene signature (ATP7A, FDX1, DBT, LIAS) was established as an independent prognostic factor, while another study constructed a signature model containing 10 genes." (PMID 41201667, 2025).
cholestasis (1 paper, 2005). Impairment of the bile flow caused by obstruction within the liver, or outside the liver in the bile duct system. "Furthermore, recent Q-PCR measurements on non-copper related hepatitis and extra hepatic cholestasis suggest that ATP7A and CP are not down-regulated by inflammation or cholestasis (data not shown)." (PMID 15790412, 2005).
diabetic retinopathy (1 paper, 2021). "The role(s) of endothelial ATP7A in physiological angiogenesis, such as in embryonic and retinal angiogenesis, as well as in pathological angiogenesis (such as tumor angiogenesis and diabetic retinopathy) needs to be explored in the future studies." (PMID 34035268, 2021).
glioblastoma (1 paper, 2025). The most malignant astrocytic tumor (WHO grade IV). "Future work incorporating ATP7A knockdown or pharmacological inhibition will be essential for validating this mechanism and further elucidating the role of copper trafficking in glioblastoma treatment." (PMID 41463095, 2025).
Hypsarrhythmia (1 paper, 2022). Hypsarrhythmia is abnormal interictal high amplitude waves and a background of irregular spikes. "Vitamin B6 allowed patients with ALDH7A1 and PNPO mutations to achieve seizure-free status, oxcarbazepine was effective for patients with SCN2A, ATP7A, WWOX, and PRRT2 mutations, and ACTH was partly effective for DOCK6 mutation patients with spasms and hypsarrhythmia." (PMID 35715422, 2022).
influenza (1 paper, 2023). An acute viral infection of the respiratory tract, occurring in isolated cases, in epidemics, or in pandemics; it is caused by serologically different strains of viruses (influenzaviruses) designated A, B, and C, has a 3-day incubation period, and usually lasts for 3 to 10 days. "Especially, “ATP7A” gene selected commonly for SC-1 and SC-2 is found to be related to virus replication process of influenza A." (PMID 37404475, 2023).
ischemia (1 paper, 2021). A hypoperfusion of the BLOOD through an organ or tissue caused by a PATHOLOGIC CONSTRICTION or obstruction of its BLOOD VESSELS, or an absence of BLOOD CIRCULATION. "To determine the role of endogenous ATP7A for ischemia-induced angiogenesis, we used ATP7Amut mice with reduced ATP7A expression and Cu transport capacity." (PMID 34035268, 2021). "Taken together, these results show that the autophagy flux is increased in ATP7A-depleted ECs stimulated with VEGF or in ATP7A dysfunctional mice in response to ischemia in which angiogenesis is impaired." (PMID 34035268, 2021). "In order to examine if ATP7A regulates autophagy during angiogenesis in vivo, we used the hindlimb ischemia model and autophagy reporter CAG-RFP-EGFP-LC3 transgenic mice crossed with or without ATP7Amut mice." (PMID 34035268, 2021). "To address the role of ATP7A in angiogenesis in vivo, we used the mouse hindlimb ischemia (HLI) model which induces ischemia by femoral artery ligation and excision, as previously reported." (PMID 34035268, 2021).
lipid metabolism disorders (1 paper, 2024). "It is also necessary to continue to explore the pathogenesis of copper and copper transporters, such as copper- transporting p-type adenosine triphosphatase 1 (ATP7A) and 2 (ATP7B), in lipid metabolism disorders." (PMID 37132140, 2024).
male fertility (1 paper, 2024). A fertility quality of inhering in a male by virtue of the bearer's disposition to initiate, sustain, or support reproduction. "Finally, studies should be undertaken to improve understanding of associations between ATP7A-related disease and male fertility." (PMID 38141875, 2024).
multiple myeloma (1 paper, 2025). "Consistent with this, we observed significantly higher expression levels of ATP7A and LOX in extramedullary multiple myeloma (EMM) patients compared to bone-marrow-confined MM patients in our previous transcriptomic analysis." (PMID 40002764, 2025).
ovarian tumors (1 paper, 2020). "Although higher ATP7A levels mediate platinum drugs resistance in different cell lines, the discrepancies in ATP7A expression have been previously found in ovarian tumors prior and after treatment, thus additional studies are needed to validate this gene as a molecular marker of resistance." (PMID 31990955, 2020).
pancreatic insufficiency (1 paper, 2024). "Notably, pancreatic insufficiency is not described as a feature of the ATP7A-related disease spectrum." (PMID 38141875, 2024).
prion disease (1 paper, 2019). A transmissible disease that is caused by a protein that is able to induce abnormal folding of normal cellular proteins, leading to characteristic spongiform brain changes, which are associated with neuronal loss without an inflammatory response. "Notably, a first Atp7a-mediated copper homeostasis link with prion diseases has been recently proposed." (PMID 31349611, 2019).
tendinopathy (1 paper, 2016). "For example, the ATP7A gene is proposed by the system to be linked to tendinopathy through four different ontology paths." (PMID 26804977, 2016).
tumor (84 papers, 2008 to 2026). "Studies have shown that copper chaperone ATOX1 is involved in the ATP7A-LOX pathway associated with tumor metastasis, and the inhibition of ATOX1 expression reduces LOX activity and the rate of cancer cell metastasis." (PMID 38200525, 2024). "ATP7A-deficient tumor cells exhibited a reduced ability to generate metastasis due to poor activation of FAK1 and low cell motility." (PMID 31540259, 2019). "Over the past two decades, numerous studies have indicated that overexpression of ATP7A/B in different tumor cell lines is associated with the development of resistance to both cisplatin and Cu with a reduced accumulation of the drug in transfected cells." (PMID 31540259, 2019). "Future studies profiling temporal dynamics of copper transporters like ATP7A could guide chronotherapy to maximize tumor susceptibility." (PMID 41480765, 2026). "The abundance of ATP7A in a variety of tumor cell lines was found to correlate with increased resistance to cisplatin, a widely used chemotherapeutic agent, and tumor transplants deficient in ATP7A were significantly more sensitive to cisplatin chemotherapy than control tumors expressing ATP7A." (PMID 39482784, 2024). "However, the remaining patients with resistant tumour lesion showed robust ATP7A expression, suggesting its association with chemoresistance." (PMID 31673101, 2019). "Considering that ATP7A/B function can facilitate tumor invasiveness and resistance to chemotherapy, many lessons from disease-causing ATP7A and ATP7B mutants could be learned to activate mechanisms that promote their loss of function in tumors." (PMID 31540259, 2019). "Indeed, deletion of ATP7A in tumorigenic fibroblasts was found to increase cisplatin sensitivity through an increased susceptibility to ROS and hypoxia, which substantially limit tumor growth in mice." (PMID 31540259, 2019). "Chromatin immunoprecipitation sequencing (ChIP-Seq) revealed elevated acetylated H3K27 (H3K27ac) enrichment at the ATP7A promoter in GSCs compared with DGCs and NSCs, indicating epigenetic activation of ATP7A in the tumor hierarchy." (PMID 41480765, 2026). "Elevated ATP7A expression has been observed in multiple cancer types, correlating with tumor growth and invasiveness." (PMID 40406488, 2025). "Upregulation of ATP7A helps tumor cells maintain copper homeostasis through copper ion efflux, thereby preventing copper-induced cellular damage." (PMID 41463095, 2025). "In our experiments, TRIM14 overexpression promoted the upregulation of ATP7A, enhancing copper efflux in tumor cells." (PMID 41463095, 2025). "ATOX1 has been implicated in regulating the ATP7A-LOX axis, a key pathway involved in tumor cell migration and metastasis." (PMID 40002764, 2025). "ATP7A can isolate platinum-based drugs into cell vesicles, reducing their contact with tumor cell DNA." (PMID 40013141, 2025). "The combination of cisplatin and D-penicillamine has been demonstrated to enhance the anti-tumor effects of oxaliplatin in oxaliplatin-resistant S3 xenograft tumors, particularly in cases with downregulated hCtr1 expression and overexpressed ATP7A." (PMID 40406488, 2025). "It has been shown that the copper-exporting protein ATP7A promotes tumor cell growth by increasing copper levels in the cells." (PMID 39539553, 2024). "In mouse models of breast cancer and lung cancer in situ, deletion of ATP7A inhibited LOX activity, leading to a significant loss of tumor growth and reduction of tumor metastasis." (PMID 38970072, 2024). "Expanding tumours actively absorb copper and utilize ATP7A/B to control the presence of this metal for oncogenic enzymes like LOX and LOX-like proteins, enhancing the invasiveness of malignant cells." (PMID 38999951, 2024). "The copper-dependent lysyl oxidase (LOX) family contributes to tumor metastasis, and its activity is dependent on the expression of ATP7A." (PMID 38200525, 2024).
tumor (continued). "In cancer cell lines, LOX activity is inhibited by silencing the ATP7A gene, which reduces tumour growth and metastatic potential." (PMID 37049685, 2023). "Several genes identified in this study, such as CDKN2A and ATP7A, have confirmed the feasibility of anti-tumor therapy in previous research." (PMID 37745054, 2023). "qRT−PCR results on CCA samples showed that FDX1, DBT were significantly downregulated in tumor tissue samples, while ATP7A was significantly upregulated." (PMID 36568224, 2022). "Our analysis also implied that the metastatic CRC patients (TNM Stage IV) had a higher expression of ATP7A in tumor tissue than locally advanced CRC patients (TNM Stage III, P<0.01)." (PMID 35265524, 2022). "ATP7A expression was significantly higher in tumor tissues than in paraneoplastic tissues, while FDX1, DBT, and LIAS expression was significantly lower than in paraneoplastic tissues (P<0.05)." (PMID 36568224, 2022). "Recent studies demonstrated that deletion of ATP7A, a copper pump, increased cisplatin sensitivity and limited tumor growth in mice." (PMID 36581992, 2022). "Together, our data indicate that KRAS-driven tumor growth is influenced by Cu-dependent mitochondrial respiration, which partly involves the biosynthetic role of ATP7A." (PMID 32709883, 2020). "How ATP7A/B trafficking is coordinated with cisplatin detoxification in tumor cells remains poorly understood." (PMID 31540259, 2019). "Although ATP7A and ATP7B are important effectors of Cu homeostasis in the body, overexpression of both proteins has been found to be associated with tumor resistance to cisplatin during chemotherapy." (PMID 31540259, 2019). "We showed that the majority of muscle-invasive bladder UC harboured resistant cells within the tumour with ATP7A upregulation." (PMID 31673101, 2019). "This suggests that ATP7A plays a key role in the activation of LOX proteins whose activities promote tumor progression and metastasis." (PMID 31540259, 2019). "In conclusion, we believe that future studies of the molecular mechanisms regulating ATP7A/B activities, interactions, and trafficking in tumor cells represent a very challenging and, at the same time, very exciting task." (PMID 31540259, 2019). "Of the remaining 21 patients with viable residual tumour lesions in RC specimen, 95% (20 of 21) showed moderate-to-strong ATP7A expression (right and 2k)." (PMID 31673101, 2019). "The data are therefore suggestive of a potential implication of TAp73/ATP7A axis in tumour suppression." (PMID 30530920, 2018). "In concert to lower copper levels, immunohistochemical staining of antibody against ATP7A on mouse tumor sections showed that cisplatin/TM double treatment (Cis/TM) reduced ATP7A protein levels as compared to untreated control (Untr)." (PMID 27806319, 2016). "The results showed that the cisplatin resistant tumor cells (CisR) exhibited extensive co-localization between cisplatin and ATP7A in the cytoplasm, suggesting that ATP7A sequesters cisplatin and prevents it from getting into the nucleus." (PMID 27806319, 2016). "We demonstrated that the ability of TM to increase tumor sensitivity to cisplatin primarily through effects on ATP7A, i.e. by reducing the amount of ATP7A protein in cisplatin resistant tumor cells." (PMID 27806319, 2016). "ATP7A expression was evaluated by immunohistochemistry in tumor tissues of unresectable NSCLC patients who received cisplatin-basing chemotherapy." (PMID 22304828, 2012). "In turn, ATP7A promoted tumor cell growth through regulation of fatty acid desaturation." (PMID 41480765, 2026). "ATP7A knockdown prolonged survival and reduced tumor burden compared with controls." (PMID 41480765, 2026). "Through its suppressive effects on SOD3, a key antioxidant gene, ATP7A may influence tumor progression." (PMID 41042257, 2025).